IRF6 (interferon regulatory factor 6)
Diseases named in the same sentence as IRF6 in open-access papers (continued):
Sharing a sentence is not in itself a finding about the gene and the disease.
glioma (8 papers, 2020 to 2026). A benign or malignant brain and spinal cord tumor that arises from glial cells (astrocytes, oligodendrocytes, ependymal cells). "Thus, we determined the expression and function of RNA-binding protein Lin28A, long noncoding RNA SNHG14, and transcription factor IRF6 in human glioma cells to elucidate the mechanism(s) underlying their role in glycolysis." (PMID 32527996, 2020). "In contrast, transcription factor interferon regulatory factor 6 (IRF6) exhibited reduced expression in glioma co-cultured endothelial cells, and its over-expression elevated the BTB permeability." (PMID 41581866, 2026). "Conversely, in renal clear cell carcinoma and glioma, IRF6 overexpression reduces xenograft growth and prolongs patient survival." (PMID 40796729, 2025). "The levels of IRF6 were lower in glioma tissues (as compared to NBTs), U87, and U251 cells (as compared to NHA)." (PMID 32527996, 2020). "Quantitative real-time polymerase chain reaction and western blotting showed that Lin28A and SNHG14 were overexpressed and IRF6 was downregulated in glioma." (PMID 32527996, 2020). "We analyzed the expression and function of Lin28A, SNHG14, IRF6, GLUT1, and PKM2 and their underlying mechanisms in the tumorigenesis of glioma." (PMID 32527996, 2020). "The schematic cartoon of the mechanism of Lin28A/SNHG14/IRF6 axis functions as a potential aerobic glycolysis enhancer in glioma." (PMID 32527996, 2020). "We generated stable IRF6-overexpressing/knockdown cell lines to investigate the role of IRF6 in glioma." (PMID 32527996, 2020). "This study reveals the oncogenic nature of Lin28A and SNHG14, while IRF6 functions as a tumor suppressor in glioma." (PMID 32527996, 2020). "In summary, the study provides novel insights into the role and function of the Lin28A/SNHG14/IRF6 axis in regulating glycometabolism in human glioma." (PMID 32527996, 2020). "Taken together, our data revealed that the Lin28A/SNHG14/IRF6 axis is crucial for reprogramming glucose metabolism and stimulating tumorigenesis in glioma cells." (PMID 32527996, 2020). "IRF6 was downregulated in glioma; overexpressing IRF6 significantly reduced aerobic glycolysis and cell proliferation, and promoted apoptosis." (PMID 32527996, 2020). "Therefore, the lin28A/SNHG14/IRF6 axis is crucial for reprogramming glucose metabolism and promoting tumor development in glioma cells." (PMID 38967893, 2024). "Subsequently, among non-coding RNAs, Linc SNHG14 was found to activate the IRF6 effect in glioma glucose metabolism by affecting the degradation of IRF6 mRNA and miR-221-5p could contribute to ischemic acute kidney injury by activating IRF6-mediated apoptosis." (PMID 37143676, 2023). "Therefore, considering the lin28a/SNHG14/IRF6 axis as a target provides novel insight for the treatment of glioma." (PMID 34178684, 2021). "This suggests that IRF6 acts as a tumor suppressor in glioma." (PMID 32527996, 2020). "Single or combination therapy targeting Lin28A, SNHG14, and IRF6 has the potential in clinical settings and may help develop new therapeutic strategies for treating glioma." (PMID 32527996, 2020). "We hypothesized that interactions within the Lin28A/SNHG14/IRF6 axis may be responsible for reprogramming glucose metabolism, thereby stimulating the development and progression of glioma." (PMID 32527996, 2020). "Since glucose metabolism is comprehensively involved in the development of cancer in cells and IRF6 was previously implicated in the regulation of glycolysis in other neural cancers, such as glioma, we next tested whether IRF6 modulates the glycolytic phenotype in neuroblastoma cells." (PMID 40796729, 2025). "Phenotypes induced by depleting SNHG14 (decreased the expression of PKM2 and GLUT1; inhibition of glycolysis and glycolytic capacity, lactate production and glucose uptake; suppression of proliferation; enhanced apoptosis) could be reversed by silencing IRF6 in glioma cells." (PMID 32527996, 2020).
glioma (continued). "In gliomas, RNA-binding protein lin28A and lncRNA SNHG14 are upregulated, while the transcription factor IRF6 is downregulated." (PMID 38967893, 2024). "Lin28a elevated the expression and stability of SNHG14, while deletion of SNHG14 increased the expression of IRF6, which inhibited the transcription of PKM2 and GLUT1 and thus impaired glycolysis and proliferation of glioma cells and induced apoptosis." (PMID 34178684, 2021). "In glioma cells, the Lin28A/SNHG14/IRF6 axis is pivotal for the reprogramming of glucose metabolism and the spurring of oncogenesis, and depletion of Lin28A reduced in vivo xenograft tumor outgrowth and prolonged nude mice survival." (PMID 34868981, 2021). "IRF6 bound the promoters of PKM2 and GLUT1, and inhibited their transcription expression, thereby impairing aerobic glycolysis and tumorigenesis in glioma." (PMID 32527996, 2020). "However, the expression and function of IRF6 in glioma remain unclear." (PMID 32527996, 2020). "Compared to the control group, overexpression of IRF6 inhibited glycolysis, decreased expression of PKM2, GLUT1, and proliferation, while stimulating apoptosis in glioma cells." (PMID 32527996, 2020). "IRF6 inhibited the transcription of PKM2 and GLUT1, thereby impairing glycolysis and cell proliferation and inducing apoptosis in glioma." (PMID 32527996, 2020). "IRF6 inhibits the transcription of PKM2 and GLUT1, impairing glycolysis in gliomas." (PMID 38967893, 2024).
tooth agenesis (7 papers, 2012 to 2025). A tooth disease characterized by failure to develop one or more missing teeth. "A common type of dental anomaly, tooth agenesis, has also been reported in association with this same IRF6 variant by our group." (PMID 23029012, 2012). "Mutation in IRF6 has been observed in 70% of families presenting with a combination of congenital lower lip pits, cleft palate alone or with cleft lip in some cases, and hypodontia." (PMID 38031027, 2023). "Patient phenotype information related to IRF6, such as hypodontia, could be incorporated in the tools to improve computational prediction." (PMID 38370976, 2024). "The genetic basis of tooth agenesis is well-established, with several genes identified as controlling factors, namely MSX1, PAX9, AXIN2, EDA, IRF6, FGFR1, and WNT10A." (PMID 40040530, 2025).
viral infection (6 papers, 2012 to 2022). "Interferon regulatory factor 6 (IRF6) belongs to a family of nine transcription factors that mediate the expression of interferon following viral infections." (PMID 34660580, 2021). "The mechanism underlying the decrease in Irf6 transcripts is uncertain, but IRF6 is known to function primarily in maintaining epidermal barrier function, not host responses to viral infection." (PMID 34591933, 2021). "The expression level of Irf6 was reduced to 14% at 12 hours and 8% at 18 hours of virus infection." (PMID 26240017, 2015). "In “NICD—Control” group IRF6 mRNA expression was increased by 1.9-fold while ΔNp63 mRNA was decreased by 40% compared to “Control- Control” group, showing that double viral infection did not interfere with the effects of Notch activation on IRF6 and ΔNp63 expression." (PMID 26161746, 2015).
cervical cancer (5 papers, 2018 to 2023). A primary or metastatic malignant neoplasm involving the cervix. "Based on our findings we hypothesized that loss of IRF6 and IL-1β expression favours cervical cancer development." (PMID 30089163, 2018). "We next wanted to determine if IL-1β and IRF6 transcripts were down regulated in cervical cancer patients." (PMID 30089163, 2018). "Additionally, cervical cancer patients with elevated expression of BNC1, EHF, and IRF6 have a decreased rate of survival relative to patients with low expression of these genes." (PMID 37627195, 2023). "Also neither IRF6 nor IL-1β mRNA levels were suppressed when analysing the data set from the TCGA cervical carcinoma cohort." (PMID 30089163, 2018).
nasopharyngeal carcinoma (5 papers, 2020 to 2024). A carcinoma arising from the nasopharyngeal epithelium. "Overexpression of IRF6 suppressed nasopharyngeal carcinoma cell proliferation and growth in vitro." (PMID 38023248, 2023). "Similar to our results, it has been reported that IRF6 directly binds the promoter of ABCG2, reduces its transcription, and decreases ABCG2 expression, thereby inhibiting proliferation and reversing the phenotype of nasopharyngeal carcinoma stem cells." (PMID 32527996, 2020).
Bartsocas-Papas syndrome (4 papers, 2016 to 2025). "While the kinase function of IKKα is dispensable for keratinocyte differentiation, RIPK4 phosphorylates IRF6 to drive nuclear translocation and regulate its transactivator activity; mutations in the kinase domain of RIPK4 that underlie Bartsocas Papas syndrome disrupt this activity." (PMID 35226783, 2022). "In addition, the RIPK4 p.Ile121Asn missense mutation, which has been identified in Bartsocas-Papas syndrome, inhibits the kinase activity of RIPK4, thereby abolishing RIPK4-mediated IRF6 and NF-κB activation." (PMID 32923402, 2020).
colorectal cancer (4 papers, 2021 to 2023). A primary or metastatic malignant neoplasm that affects the colon or rectum. "Results of our preliminary experiments indicated that the expression of IRF6 in colorectal cancer tissues was significantly lower than that in paracancerous tissues, which was positively correlated with the survival of patients with CRC." (PMID 35443865, 2022). "IRF6 might enhance chemotherapeutic sensitivity of cisplatin in colorectal cancer." (PMID 35993041, 2022). "The role of IRF6 in colorectal cancer has not been reported as far as we know." (PMID 35443865, 2022).
lung carcinoma (4 papers, 2016 to 2024). "Thus, immunotherapy resistance in a subset of lung cancer patients is associated with loss of IRF6 expression and concomitant acquisition of an EMT signature." (PMID 38378697, 2024). "Further support for this model comes from our finding that the subset of lung cancer patients whose tumors exhibited decreased IRF6 expression in the setting of immunotherapy resistance also exhibited a strong EMT signature." (PMID 38378697, 2024). "Taken together, the miR-320/IRF6 axis has been suggested as a molecular axis involved in the pathogenesis of lung cancer." (PMID 35572537, 2022). "Another study in lung cancer samples has shown up-regulation of IRF6 and down-regulation of miR-320, a miRNA that targets IRF6." (PMID 35572537, 2022). "IRF6 siRNA or miR-320 mimics could inhibit the growth and migration of lung cancer cells." (PMID 35572537, 2022).
melanoma (4 papers, 2017 to 2024). A malignant, usually aggressive tumor composed of atypical, neoplastic melanocytes. "Strikingly, in the case of DNA methylation, DNA methylation of the CpG island in the promoter region had a negative impact on the expression of IRF6 and the methylation status of IRF6 is potentially associated with the sensitivity of melanoma to interferon." (PMID 37143676, 2023). "The methylation status of IRF6 is potentially associated with the sensitivity of melanoma to interferon." (PMID 28877249, 2017). "Despite these diligent studies, little is known regarding the regulation of IRF6 by DNA methylation in melanomas or regarding the association between IRF6 methylation status and sensitivity to IFN." (PMID 28877249, 2017). "The methylation levels of 5' IRF6 CGI are potentially associated with the sensitivity of melanoma cells to IFN." (PMID 28877249, 2017). "The purpose was to determine the methylation status of the CGI located in the 5' region of IRF6 (5' IRF6 CGI) in melanoma." (PMID 28877249, 2017). "Interferon regulatory factor 6 (IRF6) is associated with the expression of interferon, which is used as an effective adjuvant therapy for melanoma, and is regarded as a tumor suppressor." (PMID 28877249, 2017). "These methylation levels were high in the melanoma cell lines with suppression of IRF6 expression and were low in the cell lines with IRF6 expression." (PMID 28877249, 2017). "The methylation level of the 5' IRF6 CGI was completely inversely correlated with cell sensitivity to interferon-β in eight examined melanoma cell lines." (PMID 28877249, 2017). "The methylation levels of the 5' IRF6 CGI ranged widely from 0.0% to 65.4% in 21 clinical melanoma samples but showed a narrow range of low levels between 0.0% to 7.2% in 24 clinical melanocytic nevus samples." (PMID 28877249, 2017). "The in vivo methylation status of IRF6 in melanomas and melanocytic nevi was analyzed by performing RT-MSP of 21 clinical melanoma samples and 24 clinical melanocytic nevus samples." (PMID 28877249, 2017). "The Kruskal-Wallis test indicated a significantly different distribution of the methylation levels of the 5' IRF6 CGI among the subtypes of melanoma (P = 0.035); the methylation levels of the acral type tended to be higher than those of the other types." (PMID 28877249, 2017). "The present study was conducted to clarify the expression and methylation status of the CGI in the 5' region of IRF6 (5' IRF6 CGI) in melanomas." (PMID 28877249, 2017). "Statistical analyses indicated a significantly different distribution of the methylation levels of the 5' IRF6 CGI among the subtypes of melanoma (Kruskal-Wallis test, P = 0.035); the acral type tended to be higher than those of the other types." (PMID 28877249, 2017). "These in vitro data encouraged us to investigate the in vivo methylation status of IRF6 in melanoma." (PMID 28877249, 2017). "This examination indicated that the CpG sites within the 5' IRF6 CGI were densely methylated in the clinical melanoma samples in which high methylation levels were detected by RT-MSP (e.g., sample #10 with a 64.2% methylation level and sample #17 with a 65.4% level)." (PMID 28877249, 2017). "IRF6 is aberrantly silenced by DNA methylation of the 5' IRF6 CGI in melanoma." (PMID 28877249, 2017). "Thus, the methylation level of the 5' IRF6 CGI was completely inversely correlated with IFN-β sensitivity in melanoma cell lines." (PMID 28877249, 2017). "Therefore, methylation analysis of the 5' IRF6 CGI may be useful for the selection of IFN-β treatment-sensitive melanomas." (PMID 28877249, 2017). "IFN-β enhanced IRF6 expression in the melanoma cell lines in which there was a considerable amount of unmethylated 5' IRF6 CGI DNA molecules but had a lower effect on IRF6 expression in melanoma cell lines that had only a small amount of unmethylated DNA molecules." (PMID 28877249, 2017). "However, little is known about the methylation status of the IRF6 gene in melanoma." (PMID 28877249, 2017).
melanoma (continued). "This suggests a relatively minor impact of IRF6 and ELOVL4 in melanoma, further emphasizing the context-dependent role of RIPK4 in both non-melanoma and melanoma skin cancers." (PMID 38656555, 2024). "The methylation status of the 5' IRF6 CGI in melanoma cell lines was analyzed using methylation-specific PCR, and the sensitivity of the same melanoma cell lines to IFN-β was analyzed using cell growth assay." (PMID 28877249, 2017). "In conclusion, IRF6 is aberrantly silenced due to DNA methylation of the CGI located in the 5' region of the IRF6 gene in melanomas, but not in melanocytic nevi." (PMID 28877249, 2017). "The present study indicated for the first time that (i) the 5' IRF6 CGI is sometimes methylated, resulting in silencing of IRF6, in melanoma but not in melanocytic nevus, and (ii) the methylation status of the 5' IRF6 CGI is potentially associated with the sensitivity of melanoma to IFN-β." (PMID 28877249, 2017).
renal clear cell carcinoma (4 papers, 2021 to 2024). "A previous study indicated that IRF6 mediated renal clear cell carcinoma cell apoptosis." (PMID 35618996, 2022). "Previous studies have reported that IRF6 mediates renal clear cell carcinoma cell apoptosis." (PMID 35618996, 2022). "In addition, our investigation on the basis of GEPIA data demonstrated that IRF6 expression was correlated strongly with the pathological stage of renal clear cell carcinoma." (PMID 33941190, 2021). "However, the expression status of IRF6 and its prognostic value in clear cell renal cell carcinoma (ccRCC) remain unclear." (PMID 34659554, 2021).
breast tumors (3 papers, 2017 to 2024). "Thus, Irf6 upregulation in patient-derived breast tumors is associated with ErbB2-targeted therapies." (PMID 30545388, 2018). "We observed that trastuzumab and lapatinib upregulate Irf6 in ErbB2-positive human breast tumor cells and that neoadjuvant trastuzumab-based therapies tend to upregulate Irf6 in human breast tumors." (PMID 30545388, 2018). "Additionally, another study demonstrated that ErbB2 inhibits the upregulation of BLNK by reducing the levels of the tumor cell transcription factor IRF6, thus facilitating breast tumor growth." (PMID 39596658, 2024).
facial cleft (3 papers, 2013 to 2023). A congenital abnormality consisting of an opening or gap in the face, which results from incomplete fusion of one or more of the embryonic facial prominences. "Studies demonstrate the interaction of IRF6 and TGFA gene polymorphisms and an increased risk of the craniofacial cleft with their simultaneous presence." (PMID 37020525, 2023). "Since some studies believed that the occurrence of the facial cleft was related to some genes related to craniofacial malformation such as IRF6, ALX1, ALX3, and ADH1C." (PMID 36090555, 2022).
invasive breast carcinoma (3 papers, 2017 to 2024). A carcinoma that infiltrates the breast parenchyma. "In breast invasive carcinoma, IRF6 showed the highest rate of alteration (6%) followed by SOX17 and MSR1 (3%)." (PMID 31879572, 2019).
ischemia (3 papers, 2017 to 2025). A hypoperfusion of the BLOOD through an organ or tissue caused by a PATHOLOGIC CONSTRICTION or obstruction of its BLOOD VESSELS, or an absence of BLOOD CIRCULATION. "This study has identified IRF6’s role as a novel PPARγ co-suppressor that suppresses PPARγ-mediated cerebrovascular endothelial cytoprotection following ischemia." (PMID 28526834, 2017). "This study is the first to report that IRF6 is a novel PPARγ co-suppressor that suppresses PPARγ-mediated cerebrovascular endothelial cytoprotection following ischemia." (PMID 28526834, 2017). "In murine models, IRF6 expression in cerebrovascular endothelial cells has been shown to promote PPARγ-related cytoprotection following ischemia, suggesting that disruption of IRF6 may impair these protective pathways." (PMID 40149423, 2025). "IRF6 acts as a PPARγ co-suppressor and directly binds to and suppresses PPARγ activity in murine cerebrovascular endothelial cells, eventually blocking PPARγ-mediated cerebrovascular endothelial cytoprotection following ischemia." (PMID 40235530, 2025).